GSTO1 (glutathione S-transferase omega 1)
Description:
Exhibits glutathione-dependent thiol transferase and dehydroascorbate reductase activities. Has S-(phenacyl)glutathione reductase activity. Also has glutathione S-transferase activity. Participates in the biotransformation of inorganic arsenic and reduces monomethylarsonic acid (MMA) and dimethylarsonic acid.
Synonyms: GSTO 1-1; SPG-R; GSTTLP28; P28; HEL-S-21
Tractability: Small molecule: a structure with a bound ligand is known; a high-quality ligand is known; it has a high-quality binding pocket. PROTAC: ubiquitination databases record sites on it; its protein half-life has been measured; a small molecule that binds it is known.
Target class: Enzyme
Chemical probes: ML175
Gene: Protein-coding gene on chromosome 10 (104,235,356 to 104,267,461, forward strand). Ensembl gene ENSG00000148834.
Subcellular location: Cytoplasm, cytosol
Pathways (Reactome):
Metabolism: Glutathione conjugation; Methylation; Vitamin C (ascorbate) metabolism
Immune System: Gene and protein expression by JAK-STAT signaling after Interleukin-12 stimulation
Gene Ontology:
Molecular function: glutathione dehydrogenase (ascorbate) activity; glutathione transferase activity; oxidoreductase activity; protein binding; methylarsonate reductase activity
Biological process: cellular response to arsenic-containing substance; L-ascorbic acid metabolic process; negative regulation of release of sequestered calcium ion into cytosol; positive regulation of release of sequestered calcium ion into cytosol; positive regulation of skeletal muscle contraction by regulation of release of sequestered calcium ion; regulation of cardiac muscle contraction by regulation of the release of sequestered calcium ion; regulation of release of sequestered calcium ion into cytosol by sarcoplasmic reticulum; xenobiotic catabolic process; glutathione metabolic process; cellular oxidant detoxification
Cellular component: cytoplasm; extracellular exosome; cytosol
Genetic constraint (gnomAD): Loss-of-function variants: 13 observed, 11.92 expected, observed/expected ratio (o/e) 1.09, 90% interval 0.71 to 1.69. The upper end of that interval is the gene's LOEUF score, 1.69, which puts it in group 6 of 6, group 1 being the genes least tolerant of losing a copy. Missense variants: 149 observed, 176.7 expected, observed/expected ratio (o/e) 0.84, 90% interval 0.74 to 0.97. Synonymous variants: 70 observed, 71.1 expected, observed/expected ratio (o/e) 0.98, 90% interval 0.81 to 1.2.
Homologues: Orthologues: chimpanzee GSTO1 (99% identical), macaque GSTO1 (97% identical), pig GSTO1 (81% identical), rat Gsto1 (77% identical), dog GSTO1 (76% identical), guinea pig GSTO1 (74% identical), rabbit GSTO1 (73% identical), mouse Gsto1 (71% identical), zebrafish gsto1 (56% identical), tropical clawed frog gsto2 (54% identical), zebrafish gsto2 (54% identical), Caenorhabditis elegans Y53G8B.1 (24% identical), and 30 more. Paralogues in human: GSTO2 (64% identical), GSTZ1 (24% identical), CLIC4 (19% identical), CLIC2 (18% identical), CLIC6 (18% identical), GSTT4 (17% identical), CLIC5 (17% identical), CLIC1 (16% identical), GSTT2 (15% identical), GSTT2B (15% identical), GDAP1 (14% identical), CLIC3 (14% identical), and 2 more.
Diseases named in the same sentence as GSTO1 in open-access papers:
GSTO1 is named in the same sentence as 94 diseases in open-access papers, as found by Europe PMC text mining. Sharing a sentence is not in itself a finding about the gene and the disease. The quoted sentences say what the papers report.
breast carcinoma (14 papers, 2008 to 2025). "In a study from Denmark, the authors limited the recruitment of patients to postmenopausal women and found an association between the homozygous GSTO1*A140D variant and breast cancer risk but only in estrogen receptor-positive cases." (PMID 40724836, 2025). "Nevertheless, in the study by Sharif, the authors found significant associations between the breast cancer risk and allele frequencies of both the variant A allele of GSTO1*A140D (C419A; rs4925) and the G allele of GSTO2*N142D (A424G; rs156697)." (PMID 40724836, 2025). "Polymorphisms in GSTM1, GSTP1, and GSTO1 enzymes increase the risk of developing breast cancer and hepatocellular carcinoma." (PMID 26682223, 2015). "A study in a Taiwanese population identified a significant association between the Asp140 variant of the GSTO1 gene variant and hepatocellular carcinoma, cholangio-carcinoma, and breast cancer." (PMID 18414634, 2008). "In the already mentioned study by Marahatta on a small group of subjects from Thailand, authors found a significantly higher gene frequency of the GSTO1*A140D variant (heterozygous or homozygous carriers) in breast cancer patients, as compared to the control group." (PMID 40724836, 2025). "Indeed, the same authors found a GSTO1-1 protein deficiency in a T-47D breast cancer cell line hemizygous for the E155del variant and a reduction in the GSTO1-1 activity in lymphoblastoid cell lines heterozygous for the delE155/K208 haplotype." (PMID 40724836, 2025). "Authors found a significantly different genotypic distribution for the GSTO1*A140D variant in HCC, cholangiocarcinoma, and breast cancer, as compared to the control group." (PMID 40724836, 2025). "GSTO1 overexpression has been found in several cancers, such as esophageal cancer, lung cancer, breast cancer, kidney cancer, and bladder cancer." (PMID 38750006, 2024). "Some studies show that GSTO1-1 is highly expressed in transitional cell carcinoma, esophageal squamous cell carcinoma, pancreatic cancer, and breast cancer." (PMID 36688005, 2023). "For instance, RyR1s contribute to acquired chemo-resistance by executing non-enzymatic interactions with chemotherapy-induced GSTO1 (glutathione S-transferase omega 1) to fine-tune cytosolic Ca2+ levels needed for the enrichment of the tumor-initiating breast cancer stem cells (BCSCs)." (PMID 32599788, 2020).
bladder cancer (7 papers, 2012 to 2025). "Contrary to the study by Hsu on Taiwanese subjects, authors found a positive association between arsenic exposure (the uppermost quartile, 3.72 μg/L in drinking water) and bladder cancer in subjects homozygous for the wild-type GSTO1*A140 variant." (PMID 40724836, 2025). "Subjects treated with epirubicin, expressing homozygous wild-type GSTO1 (GSTO1 A140, GSTO1 CC genotype), had a lower risk for bladder cancer recurrence (RFS) and a longer mean survival time (MST), as compared with the GSTO1 AC+AA genotype." (PMID 40724836, 2025). "Our analysis of protein expression in bladder cancer cells stimulated by secretions from tumor‐associated macrophages (TAMs) showed a significant increase in GSTO1." (PMID 38750006, 2024). "Unexpectedly, GSTO1‐associated EVs attenuated the migration and colony formation of bladder cancer cells." (PMID 38750006, 2024). "In contrast, the Pt content was significantly lower in purified EVs derived from GSTO1‐KO cells, suggesting that GSTO1‐associated EVs contributed to Pt efflux from bladder cancer cells." (PMID 38750006, 2024). "In bladder cancer, the expression of glutathione S‐transferase omega 1 (GSTO1) can be induced by tumor‐associated macrophage‐secreted tumor necrosis factor‐alpha." (PMID 38750006, 2024). "Time‐lapse observation of EV formation in bladder cancer cells expressing GSTO1‐GFP was performed to characterize GSTO1‐associated EVs." (PMID 38750006, 2024). "However, the potential involvement of GSTO1 in drug resistance and its underlying mechanism within the realm of bladder cancer remain unexplored." (PMID 38750006, 2024). "In conclusion, GSTO1‐mediated EV release may contribute to cisplatin resistance caused by TAMs in bladder cancer." (PMID 38750006, 2024). "Upregulation of GSTO1 expression is reported for diverse cancers, including esophageal squamous cell carcinoma, colorectal cancer, non‐small‐cell lung cancer, and bladder cancer, and is associated with metastatic features and advanced cancer stages." (PMID 38750006, 2024). "The increased presence of GSTO1 in bladder cancer has been linked to tumor progression." (PMID 38750006, 2024). "In addition, patients carrying two C alleles for GSTO1 rs4925 had a lower risk of bladder cancer recurrence (CC/(AC+AA): HR = 0.51, 95% CI = 0.27–0.95)." (PMID 26354850, 2015). "GSTT1 active, GSTO1 Asp140Asp or GSTO2 Asp142Asp genotypes were independent predictors of a higher risk of death among bladder cancer patients (HR = 2.5, P = 0.028; HR = 2.9, P = 0.022; HR = 3.9, P = 0.001; respectively) and significantly influenced the overall survival." (PMID 24040330, 2013). "The overexpression of GSTO1 leads to the acquisition of cisplatin resistance, as it facilitates cisplatin efflux by releasing large EVs from bladder cancer cells." (PMID 38750006, 2024). "Taken together, these results suggest that GSTO1 enhances cisplatin resistance in bladder cancer by activating EV release to efflux intracellular cisplatin." (PMID 38750006, 2024). "On the other hand, GSTO1 knockout and treatment with a GSTO1 inhibitor sensitized bladder cancer cells to cisplatin cytotoxicity." (PMID 38750006, 2024). "Under cisplatin treatment, GSTO1 overexpression increased the ability of bladder cancer to resist cisplatin cytotoxicity." (PMID 38750006, 2024). "The bladder cancer tissue array analysis (n = 185) resulted in a higher GSTO1 histochemistry score (H‐score) for bladder tumors (n = 169) than for normal bladder tissue (n = 16)." (PMID 38750006, 2024). "The present study showed that secretory TNF‐α from TAMs induced GSTO1 expression in bladder cancer cells, which in turn contributed to the generation of large EVs for cisplatin efflux." (PMID 38750006, 2024). "GSTO1‐OE increased cisplatin resistance, whereas GSTO1‐KO or the GSTO1 inhibitor GSTO1‐IN‐1 sensitized bladder cancer to cisplatin." (PMID 38750006, 2024).
bladder cancer (continued). "Our data indicate that TAMs are capable of inducing GSTO1 expression in bladder cancer by secreting tumor necrosis factor‐alpha (TNF‐α)." (PMID 38750006, 2024). "Collectively, these results suggest functional roles for GSTO1 in both intrinsic and acquired cisplatin resistance in bladder cancer." (PMID 38750006, 2024). "The present study shows the possible role of GSTO1 in TAM‐mediated cisplatin resistance in bladder cancer." (PMID 38750006, 2024). "The data revealed that patients with recurrent bladder cancer after cisplatin treatment exhibited higher levels of GSTO1 expression." (PMID 38750006, 2024). "GSTO1 has been reported to be upregulated in several human cancers including esophageal squamous cell carcinoma, colorectal, and urinary bladder cancer." (PMID 37894945, 2023). "GSTO1 (rs4925) and GSTO2 (rs156697) genotypes have been associated with worse prognosis and shorter survival in bladder cancer patients." (PMID 31924810, 2020). "In the present study, we investigated the possible association between SNPs in the GSTP1, GSTO1, GSTO2, and ABCB1 genes with response to treatment in patients with bladder cancer." (PMID 26354850, 2015). "A significantly reduced risk of bladder cancer recurrence was found in patients simultaneously carrying the GSTP1 AA and GSTO1 CC genotypes, when compared to patients carrying other combinations of genotypes (HR = 0.21, 95% CI = 0.08–0.56)." (PMID 26354850, 2015). "The development of strategies that target GSTO1 may hold promise for improving therapeutic efficacy against bladder cancer in the future." (PMID 38750006, 2024). "This prompted further investigation into the role of GSTO1 in bladder cancer." (PMID 38750006, 2024). "Therefore, in this study, we focused on exploring the roles of GSTO1 in chemoresistance in bladder cancer." (PMID 38750006, 2024). "Strategies to target GSTO1 could potentially improve the efficacy of cisplatin in treating bladder cancer." (PMID 38750006, 2024). "Single nucleotide polymorphisms (SNPs) in GSTO-1, As3MT and MTHFR were genotyped using DNA from 219 bladder cancer cases and 273 controls participating in a case–control study in Southeastern Michigan and exposed to low to moderate (<50 μg/L) levels of arsenic in their drinking water." (PMID 22747749, 2012). "Specifically, there was evidence of a positive association between arsenic exposure and bladder cancer among those homozygous wildtype for the GSTO-1 polymorphism that was not present for those with at least one variant allele." (PMID 22747749, 2012). "In addition, the expression of GSTO1 was increased in cisplatin‐resistant bladder cancer cells." (PMID 38750006, 2024). "We did not observe any significant associations between SNPs in GSTO-1, As3MT and MTHFR and bladder cancer risk overall with one exception." (PMID 22747749, 2012). "However, the role of GSTO1 in drug resistance, specifically in bladder cancer, has never been investigated." (PMID 38750006, 2024).
colorectal cancer (7 papers, 2016 to 2025). A primary or metastatic malignant neoplasm that affects the colon or rectum. "GSTO1-1 upregulation has been reported in various cancers, including pancreatic cancer, esophageal adenocarcinoma, colorectal cancer, and ovarian cancer, where the upregulation has been associated with drug resistance." (PMID 40724836, 2025). "CRISPR/Cas9 mediated knocking out of glutathione S-Transferase Omega 1 (GSTO1) in colorectal cancer cells enhances the cytotoxicity of chemotherapeutics, including cisplatin and oxaliplatin." (PMID 39696697, 2024). "We also noted that GSTO1 expression was higher in several colorectal cancer patient tumours as compared with normal colon tissue, consistent with our bioinformatics analysis." (PMID 27703239, 2016). "Our findings demonstrate the therapeutic utility of GSTO1 inhibitors as anticancer agents and identify the novel cellular pathways under GSTO1 regulation in colorectal cancer." (PMID 27703239, 2016). "One study showed that knocking out glutathione S-transferase omega 1 (GSTO1) in colorectal cancer cells using the CRISPR/Cas9 system could enhance the cytotoxicity of chemotherapy drugs, including cisplatin and oxaliplatin." (PMID 35715750, 2022). "Moreover, nuclear localization of GSTO1 in Barrett’s esophagus and colorectal carcinoma suggests its probable involvement in the protection of specific nuclear components in conditions of oxidative stress, thus promoting malignant transformation." (PMID 31861116, 2019). "Another class of α-chloroacetamide compounds has been synthesized by Ramkumar and colleagues, among which C1-27 is recognized as the most potent GSTO1-1 inhibitor showing promising antitumor activity in both in vitro and in vivo models of colorectal cancer, without gross systemic toxicities." (PMID 30487385, 2018). "Taken together, these results demonstrate that C1-27 targets GSTO1 in tumours and shows promising antitumour activity in both cell line xenograft and PDX models of colorectal cancer, without gross systemic toxicities." (PMID 27703239, 2016).
Parkinson disease (7 papers, 2012 to 2025). A progressive degenerative disorder of the central nervous system characterized by loss of dopamine producing neurons in the substantia nigra and the presence of Lewy bodies in the substantia nigra and locus coeruleus. "A genetic study showed previously that the minor variant of SNP rs4925 in GSTO1 was linked to a delayed onset of AD by 7 years and Parkinson's disease by 9 years." (PMID 40189792, 2025). "Li and colleagues also detected significantly lower GSTO1 levels in the hippocampus of AD patients compared to controls, and alleles of GSTO1 are significantly associated with age-at-onset for AD and Parkinson’s disease (PD)." (PMID 26829228, 2016). "GSTO1 is an omega class subtype of glutathione S-transferases (GST), and genetic variants of the omega class GST genes are related to the age of onset of diseases such as AD, Parkinson’s disease, amyotrophic lateral sclerosis, and vascular dementia." (PMID 38912047, 2024). "Furthermore, single-nucleotide polymorphisms (SNPs) in human GSTO1 and GSTO2 have been associated with the age at onset of Alzheimer’s disease (AD) and Parkinson’s disease (PD)." (PMID 32674363, 2020). "Glutathione S-transferase omega-1 and 2 genes (GSTO1, GSTO2), residing within an Alzheimer and Parkinson disease (AD and PD) linkage region, have diverse functions including mitigation of oxidative stress and may underlie the pathophysiology of both diseases." (PMID 22494505, 2012).
Obesity (5 papers, 2017 to 2024). Accumulation of substantial excess body fat. "GstO1 is closely associated with human diseases such as cancers, neurological diseases, inflammation, and obesity." (PMID 38791319, 2024). "GSTK1 and GSTO1 are glutathione transferases that play an important role in inflammatory processes such as obesity, insulin resistance, and lipid peroxidation induced by high‐fat diets." (PMID 38894980, 2024). "The inhibition of GstO1 suppressed LPS-induced inflammation, and the high-fat-diet-induced obesity was significantly reduced in the GstO1 knock-out mice." (PMID 38791319, 2024). "Whole body deletion of GSTO1 increases resistance to inflammatory lipopolysaccharides and diet-induced obesity." (PMID 35964946, 2022). "This study has identified GSTO1-1 as a novel target for the development of drugs for the treatment of inflammation mediated via TLR4 and possibly the treatment of the inflammation associated with obesity." (PMID 29259211, 2017). "In the present investigation, we found that GSTO1-1 deficient mice consuming a high fat diet present a similar phenotype to that of TLR4 and MyD88 deficient mice and do not exhibit marked obesity and insulin resistance." (PMID 29259211, 2017).
Alzheimer disease (4 papers, 2016 to 2024). A progressive, neurodegenerative disease characterized by loss of function and death of nerve cells in several areas of the brain leading to loss of cognitive function such as memory and language. "Glutathione S-transferase omega-1 (GSTO1) is closely associated with the pathogenesis of Alzheimer’s disease (AD)." (PMID 39763578, 2024). "Multiple resources including Chillibot, Alzheimer Disease & Frontotemporal Dementia Mutation Database, the ALZGENE database, and Pubmed were used to determine whether members of the Gsto1 coexpression network had been previously associated with AD or other neurodegenerative disorders." (PMID 26829228, 2016).
Cognitive impairment (4 papers, 2016 to 2024). Abnormal cognition is characterized by deficits in thinking, reasoning, or remembering. "Western blot analysis showed that the upregulation of GSTA1 in the CA1 area and the downregulation of GSTO1 in the hippocampus were linked to cognitive impairment, commonly seen in aging animals." (PMID 35767571, 2022). "In the present study, we showed for the first time a significant association of GSTO1*C with mild cognitive impairment." (PMID 27259244, 2016). "Therefore, we examined, whether individual neuropsychological tests, especially MMSE, achieved the classification accuracy required for detecting significant associations of APOE4 or GSTO1*C with cognitive impairment." (PMID 27259244, 2016). "It has been reported that GSTO1 expression levels are significantly reduced in patients with cognitive impairment, and a significant correlation between GSTO1 polymorphism and the age of AD onset has been found." (PMID 38912047, 2024). "However, association of GSTO1*C with cognitive impairment was previously not observed." (PMID 27259244, 2016).